DLL3 (delta like canonical Notch ligand 3)
Diseases named in the same sentence as DLL3 in open-access papers (continued):
Sharing a sentence is not in itself a finding about the gene and the disease.
neuroendocrine carcinoma (continued). "We evaluated DLL3 expression in 1294 NEN and 479 non-neuroendocrine carcinomas, correlating the findings with histological subtypes, tumour localisation, and overall survival (OS)." (PMID 40153138, 2025). "Several DLL3-targeted therapies are being developed for the treatment of SCLC and other neuroendocrine carcinomas, including antibody-drug conjugates (ADCs), T-cell engager (TCE) molecules, and chimeric antigen receptor (CAR) therapies." (PMID 37355629, 2023). "DLL3, an inhibitory NOTCH ligand, is overexpressed in many neuroendocrine cancers and is a downstream target of ASCL1." (PMID 29088717, 2017). "From these analyses, we found that DLL3 did not constitute a genetic dependency in neuroendocrine cancer cell lines." (PMID 39874041, 2025). "While these recent findings have strengthened the position of DLL3 as a protein of interest for these hard-to-treat cancers, limited data preclude conclusions about DLL3’s potential therapeutic role in other types of pulmonary NEN, extrapulmonary NEN and also non-neuroendocrine carcinomas." (PMID 40153138, 2025). "The DLL3-targeting T Cell engager BI 764532 is currently being evaluated in the DAREONTM-5 open-label, multicenter phase II dose-selection trial, in patients with relapsed/refractory neuroendocrine carcinomas (NCT05882058)." (PMID 38893145, 2024). "While mechanisms of Notch pathway suppression in neuroendocrine cancers are not entirely clear, it is known that the cell surface Notch ligands such as delta-like 3 (DLL3) inhibit Notch pathway activation in normal development." (PMID 39416174, 2024). "Our potent DLL3-targeting CAR T cells could serve as an important addition to the treatment armamentarium for patients with SCLC and other DLL3+ neuroendocrine cancers." (PMID 36951942, 2023). "High-grade neuroendocrine carcinomas were negative for DLL3, and five-year OS and PFS were significantly improved in patients who received adjuvant chemotherapy." (PMID 36071128, 2022). "DLL3-based therapies may be effective in many NEC and pulmonary carcinoids, while DLL3 appears to be a minor therapeutic target for GEP-NET and non-neuroendocrine carcinomas." (PMID 40153138, 2025). "DLL3 is frequently expressed in neuroendocrine carcinomas (NEC), notably small-cell and large-cell variants, while being uncommon in well-differentiated GEP-NETs, supporting DLL3 as a therapeutic target primarily in NEC rather than NET." (PMID 41300999, 2025). "Our study systematically investigated DLL3 expression in a comprehensive cohort of 1294 NEN and 479 non-neuroendocrine carcinomas, revealing significant differences not only between NEC and NET in general, but also among their various histological subtypes, grades, and anatomic localisations." (PMID 40153138, 2025).
lung carcinoma (17 papers, 2017 to 2025). "Combined, these findings suggest that TTF1 protein expression (a routine clinical diagnostic IHC marker for lung cancer) could be a surrogate marker for DLL3 expression and, thus, help identify patients with DLL3-positive tumors (which have the highest response rates to rovalpituzumab tesirine)." (PMID 29088717, 2017). "While several common biomarkers are associated with lung cancer, including EGFR, ALK, KRAS, ROS1, HER2, and others, the high expression of DLL3 in SCLC has emerged as a promising new target for therapeutic intervention." (PMID 40177519, 2025). "We evaluated DLL3 expression in patients with neuroendocrine-transformed EGFR-mutant lung cancer and present two cases of tarlatamab treatment in EGFR-mutant SCLC." (PMID 41256964, 2025). "In this study, neuroendocrine-transformed EGFR-mutant lung cancer exhibited variable DLL3 expression." (PMID 41256964, 2025). "We evaluated DLL3 expression in patients with neuroendocrine-transformed EGFR-mutant lung cancer and present two cases who received tarlatamab." (PMID 41256964, 2025). "In this study, we identified variable expression of DLL3 by IHC in neuroendocrine-transformed tissue of EGFR-mutant lung cancer resistant to osimertinib." (PMID 41256964, 2025). "The 80% expression of DLL3 on SCLC lung cancer cells makes it a suitable target for treatment with targeted drugs, including immunotoxins." (PMID 40177519, 2025). "A series of antigens targeting surface proteins, including EGFR, CEA, MSLN, HER2, ROR1, MUC1, and DLL3 in lung carcinoma cells have been incorporated into CAR structure to allow CAR-T cells target lung cancer tissue." (PMID 40624569, 2025). "Despite the growing body of knowledge on the role of DLL3 in lung cancer, there remains a significant gap in our understanding of the actual expression rate of DLL3 when assessed by immunohistochemistry (IHC) in routine clinical laboratories." (PMID 39392394, 2024). "DLL3 is found to be expressed in approximately 80% of neuro-endocrine PCs and lung carcinomas, making it an attractive candidate for therapeutic interventions." (PMID 37835533, 2023). "SCAN-ACT identified 174 monospecific CAR-T targets in GBM, including several established GBM CAR-T targets such as CD276, EGFR, IL13RA2, ROBO1, as well as targets studied in different diseases like GPC2 in neuroblastoma, IL11RA in osteosarcoma, or DLL3 in lung cancer." (PMID 40814001, 2025). "Small-cell (n = 1) lung carcinoma expressed DLL3 moderately, and large-cell neuroendocrine carcinomas (n = 2) of the lung demonstrated strong DLL3 positivity (50–90% of cells; average H-score 180 combined, range 120 to 270) in all the tumors examined, including metastatic foci." (PMID 40699376, 2025). "DLL-3 is an inhibitory Notch pathway ligand that mediates oncogenesis in melanoma, bladder, endometrial, ovarian, pancreatic, and lung cancer via multiple mechanisms, including angiogenesis, tumour stromal remodelling, and effects on immune cells in the tumour stroma." (PMID 37631232, 2023). "Additionally, previous studies have shown a favorable correlation between the pathological stage of lung cancer and DLL3 expression on lung cells." (PMID 37179118, 2023). "TTF1 (used in the diagnosis lung cancer) could therefore be used as a surrogate of DLL3 expression to identify patients who may respond to the DLL3 antibody-drug conjugate rovalpituzumab tesirine." (PMID 29088717, 2017). "Dll3 can stimulate growth, migration and invasion of lung cancer cells." (PMID 28482837, 2017). "Research on several antigens, including c-MET, DLL3, FAP, and B7-H3 (CD276), has been conducted concerning lung cancer treatment." (PMID 38694508, 2024). "CAR-T cells targeting EGFR variant III, mesothelin, Erythropoietin-producing hepatocellular carcinoma A2 (EphA2), Delta-like 3 (DLL3), PSCA- and MUC-1, and PD-L1 have shown significant antitumor effects against lung cancer cells in vitro and in vivo." (PMID 37420216, 2023).
lung carcinoma (continued). "DLL3 is frequently expressed in SCNE lung carcinomas but not detectable in normal adult tissues, however, a recently published clinical trial using antibody–drug conjugate targeting DLL3 has failed." (PMID 37467967, 2023). "In addition, most studies have demonstrated that DLL3 is highly expressed in SCLC, while it is not or is less expressed in other types of lung cancer and normal tissues." (PMID 32847588, 2020).
breast carcinoma (14 papers, 2014 to 2025). "Notably, overexpression of DLL3 was associated with shorter OS in endometrial cancer, ovarian cancer, breast cancer and Small-cell Bladder Cancer." (PMID 37274780, 2023). "Notably, overexpression of DLL3 was associated with shorter overall survival (OS) in endometrial cancer, ovarian cancer, breast cancer and small-cell bladder cancer." (PMID 37274780, 2023). "Among the selected gene signatures, DLL3 has been found high expression in breast cancer and was an independent prognostic factor for OS." (PMID 36880837, 2023). "For example, the abnormal activation of the receptor-ligand pairs, DLL3-Notch3, is related to the development of breast cancer, non-small cell lung cancer, and hematological malignancies." (PMID 36777724, 2023). "Additionally, three candidate genes are associated with Breast cancer (DLL3, BRCA2, WNT2B), the mTOR signaling pathway (WNT2B, TELO2, TNFRSF1A), and Pathways in cancer (DLL3, BRCA2, WNT2B)." (PMID 40919429, 2025). "The Notch signaling system that contains four Notch receptors (Notch1- Notch4) and five canonical ligands (Dll1, Dll3, Dll4, Jagged1 and Jagged2), plays important roles including carcinogenesis, cancer stem cell renewal, angiogenesis, and chemotherapy resistance in the progression of breast cancer." (PMID 33413403, 2021). "For instance, targeting Lgr5 in colorectal cancer, DLL3 in pulmonary neuroendocrine tumors, and CXCR1 in breast cancer has been reported to reduce the CSC population." (PMID 39420119, 2024). "In tumors such as breast cancer, various members of the Notch pathway, including Notch1, Notch3, DLL1, and DLL3, have been implicated in either promoting or inhibiting angiogenesis." (PMID 40486870, 2025).
large cell neuroendocrine carcinoma (13 papers, 2019 to 2025). A usually aggressive carcinoma composed of large malignant cells which display neuroendocrine characteristics. "The mammalian Notch family ligands delta‐like 3 (DLL3) is reported to be a potential therapeutic target for large cell neuroendocrine carcinomas (LCNEC)." (PMID 32691982, 2020). "Multi-omics analyses across pulmonary carcinoids, large cell neuroendocrine carcinomas (LCNEC), and SCLC further substantiate DLL3’s therapeutic candidacy." (PMID 40496850, 2025). "DLL3 is highly expressed in SCLC and large-cell neuroendocrine carcinoma (LCNEC) models and minimally expressed in normal tissues." (PMID 36381237, 2022). "DLL3 surface expression correlated with time to tumor progression in 10 SCLC and 1 large cell neuroendocrine carcinoma (LCNEC) patient-derived xenograft models." (PMID 31215500, 2019). "However, in contrast to pulmonary SCNEC, data regarding DLL3 expression in extrapulmonary SCNEC, pulmonary and extrapulmonary large cell NEC (LCNEC), mixed neuroendocrine-non-neuroendocrine neoplasms (MiNEN), gastroenteropancreatic NET (GEP-NET), and pulmonary carcinoids is scarce." (PMID 40153138, 2025).
prostate carcinoma (12 papers, 2019 to 2026). A carcinoma that arises from epithelial cells of the prostate gland. "In prostate cancer, DLL3 is highly expressed in a subset of advanced metastatic samples and is not notably expressed in non-metastasis samples or benign tissues." (PMID 36338696, 2022). "DLL3 can be targeted by the antibody-drug conjugate SC16LD6.5 (Rovalpituzumab Tesirine); treatment with this antibody resulted in complete and durable response in DLL3+ prostate cancer xenograft models." (PMID 31366128, 2019). "While previous studies have shown DLL3 regulates proliferation and migration in cancers such as gastric and prostate cancer, reports on its regulation in UCEC are absent." (PMID 40066092, 2025). "With regard to metastatic castration-resistant prostate cancer, though there are no ADCs approved for prostate cancer, there are some ADCs targeting different antigens in clinical studies, such as PSMA, TROP-2, STEAP1, TF and DLL-3." (PMID 40959458, 2025).
glioblastoma (11 papers, 2016 to 2025). The most malignant astrocytic tumor (WHO grade IV). "DLL-3 is associated with the proneural subtype of glioblastomas which is considered to be the least malignant and most treatment-sensitive of the molecular glioblastoma subtypes." (PMID 29523123, 2018). "Nevertheless, research also suggests that DLL3 can exert tumor-suppressive effects, as observed in studies of hepatocellular carcinoma and glioblastoma." (PMID 40066092, 2025). "Our analysis of human cell lines, multiple patient cohorts (including both SCLC and glioblastoma), and mouse models revealed a strong, positive correlation between the expression of DLL3 and TTF1." (PMID 29088717, 2017). "We further validated the regulation role of METTL3 in DLL3, NOTCH3, and HES1 and identify its influence in cell proliferation of glioblastoma cell lines via cell experiments." (PMID 34589481, 2021). "We further compared the correlation between TTF1 and DLL3 protein in cell lines, and NKX2-1 and DLL3 mRNA in cell lines, an additional SCLC patient cohort and a cohort of glioblastoma patient samples and found significant correlations in each dataset." (PMID 29088717, 2017). "The correlation between DLL3 and NKX2-1 in glioblastoma is notable as rovalpituzumab tesirine is indicated for glioblastoma in an ongoing basket trial (NCT 02709889) and requires DLL3 expression for enrollment." (PMID 29088717, 2017). "In this study, we correlated glioblastoma locations with the expression of five mesenchymal genes (VEGFC and its receptor FLT4, HGF and its receptor MET, and CHI3L1) and five proneural genes (PROM1, NOTCH1, DLL3, PDGFRA, and BCAN)." (PMID 26637806, 2016). "In particular, transcriptomic analyses showed a mesenchymal profile for periventricular glioblastoma stem-like cell line, with overexpression of VEGFC and CHI3L1 and a proneural profile for cortical glioblastoma stem-like cell line with overexpression of PROM1, DLL3, and BCAN." (PMID 26637806, 2016). "Regardless, Dll3 expression, if present in a IDH-wild type Glioblastoma, is generally restricted to non-mesenchymal subtypes." (PMID 30832246, 2019).
melanoma (9 papers, 2011 to 2025). A malignant, usually aggressive tumor composed of atypical, neoplastic melanocytes. "For melanoma, knockdown of DLL3 inhibits inflammatory stimulation-induced melanoma cell migration and invasion by blocking Twist1-mediated epithelial-mesenchymal transition (EMT)." (PMID 36338696, 2022). "Then, we identified 9 LR pairs (“BMP6- > HJV” 、"CCL8- > ACKR4” 、"DLL3- > NOTCH3"、"DSC3- > DSG3"、"GHRH- > GHRHR” 、"LRRC4B- > PTPRF"、"SEMA4D- > PLXNB1"、"SFRP1- > FZD6"、"UCN- > CRHR1′′) as key LR pairs in melanoma prognosis through Lasso Cox regression and Multiple Stepwise Regression." (PMID 36777724, 2023). "DLL3 was found highly expressed in melanoma compared with normal skin, and using Rovalpituzumab tesirine, a DLL3-targeting antibody-drug conjugate, can have antitumor activity in melanoma patients." (PMID 36777724, 2023). "Substantiated investigations have elucidated that the downregulation of DLL3 can attenuate lipopolysaccharide-induced inflammation, inhibit migration, and impede invasion of melanoma cells through the inhibition of Twist1-mediated epithelial-mesenchymal transition." (PMID 38036577, 2023). "Furthermore, we report for the first time that aberrant NOTCH signaling can predict clinical outcome in melanoma, with high HES1 and DLL3 levels associated with shorter post recurrence survival." (PMID 21980408, 2011). "On the other hand, high DLL3 expression was associated with poorer prognoses in melanomas (HR, 1.32; 95% CI, 1.22–1.44; P < 0.001), non-SCLCs (HR, 1.13; 95% CI, 1.09–1.18; P < 0.001), and female genital tract malignancies (HR, 1.24; 95% CI, 1.07–1.44; P = 0.004)." (PMID 39874041, 2025). "The results showed that the expression of DSC3, DLL3, BMP6, SEMA4D, and GHRH are increased (p < 0.05) in melanoma, while the expression of LRRC4B, SFRP1, DCN, and CCL-8 decreased in melanoma (p < 0.05)." (PMID 36777724, 2023).
spondylocostal dysostosis (9 papers, 2007 to 2025). Spondylocostal dysplasia is a rare genetic disorder characterized by defects of the bones of the spine (vertebrae) and abnormalities of the ribs. "Jarcho-Levin syndrome has been linked to several genes, including DLL3 that is associated with the Notch pathway." (PMID 40538613, 2025). "The Dll3 mutation in the human causes spondylocostal dysostosis (SCDO1) also with malformation of ribs, vertebral bodies, and intervertebral discs." (PMID 38252118, 2024). "The pudgy mouse caused by the Dll3 mutation shows the spondylocostal dysostosis (SCDO1) profile in humans." (PMID 38252118, 2024). "Mutations in human DLL1 induce neurodevelopmental disorders with non-specific brain abnormalities, whereas mutations in DLL3 cause spondylocostal dysostosis with axial skeletal defects." (PMID 35422684, 2022). "Evidence for genetically heterogeneous etiologies of vertebral malformations includes the identification of mutations in DLL3 in patients with spondylocostal dysostosis and mutations identified in JAG 1 in patients with Alagille syndrome." (PMID 17888180, 2007). "Expression of DLL3 is highest in fetal brain and paraxial mesoderm, and mutations in the DLL3 gene cause the autosomal recessive genetic disorder Jarcho-Levin syndrome characterized by spondylocostal dysostosis." (PMID 40699376, 2025). "To date, there have been 28 reported DLL3 mutations resulting in a form of spondylocostal dysostosis (SCDO), SCDO1, which is a type of vertebral malformation." (PMID 38348091, 2023).
hepatocellular carcinoma (7 papers, 2013 to 2025). A malignant tumor that arises from hepatocytes. "Further, DLL3 has been shown to be silenced by methylation in human hepatocellular carcinoma (HCC), leading to restricted growth of cancer cells." (PMID 26407342, 2015). "For example, overexpression of DLL3 induces cellular apoptosis in human hepatocellular carcinoma." (PMID 36338696, 2022). "By analyzing genes from human hepatocellular carcinoma (HCC) with restriction landmark genomic scanning, several aberrantly methylated genes, including Delta-like 3 (DLL3), have been isolated." (PMID 23337976, 2013).
endometrial cancer (6 papers, 2020 to 2025). Primary or metastatic malignant neoplasm involving the endometrium (mucous membrane that lines the endometrial cavity). "Kaplan–Meier curves and the log-rank test showed that the increased expression of DLL3 is also associated with shorter overall survival in patients with endometrial cancer (p = 0.0045)." (PMID 39518001, 2024). "The association of DLL3 expression with more aggressive tumor behavior was also found in patients with other high-grade tumor types, such as endometrial carcinoma, lung adenocarcinoma, and small cell bladder cancer, as well as in SCLC patients." (PMID 34568063, 2021). "High DLL3 expression was associated with bad OS and usually expressed in older patients and advanced stage in endometrial cancer." (PMID 32847588, 2020). "Current data have demonstrated that DLL3 expression may be a potential new oncological marker for early diagnosis and prognosis in patients with endometrial cancer." (PMID 39518001, 2024). "For example, overexpression of upregulated DLL3 is an independent prognostic predictor for endometrial cancer and could be a potential and novel tumor marker for early-stage endometrial cancer." (PMID 33193589, 2020). "Further analysis through cell line studies, comparing HEEC with endometrial cancer cell lines (HEC-1-A and AN3CA), revealed that DLL3 expression levels in HEC-1-A and AN3CA cell lines were significantly elevated compared to HEEC." (PMID 40066092, 2025). "The level of DLL3 expression was significantly increased in the endometrial cancer tissue compared to the non-tumor tissue (p < 0.0003)." (PMID 39518001, 2024).